PDGFRA (platelet derived growth factor receptor alpha)
Diseases named in the same sentence as PDGFRA in open-access papers (continued):
Sharing a sentence is not in itself a finding about the gene and the disease.
gastrointestinal stromal tumor (continued). "In gastrointestinal stromal tumors (GIST), mutations of exons 9, 11, 13 and 17 of KIT, and of exons 12, 14 and 18 of PDGFRA are key drivers of oncogenesis and are present in around 85–90% of tumors, whereas the remaining 10–15% of these cancers is referred as KIT/PDGFRA wild-type GISTs." (PMID 34638228, 2021). "In most gastrointestinal stromal tumors (GISTs), genetic alterations of KIT or platelet-derived growth factor A (PDGFRA) gene that activate their functions are detected, while wild-type GIST, in which these genetic alterations are not detected, accounts for approximately 10% of all GISTs." (PMID 31974683, 2020). "Gastrointestinal stromal tumours that are wild type for KIT and PDGFRA are referred to as WT GISTs." (PMID 33199729, 2020). "Approximately 80% of gastrointestinal stromal tumors (GIST) carry pathogenic activating mutations of proto-Oncogene c-Kit (KIT), while 5% to 10% harbor activating mutations of the platelet-derived growth factor receptor alpha (PDGFRA), both members of the type III class of tyrosine kinase receptors." (PMID 29510530, 2018). "Gastrointestinal stromal tumors (GISTs) with no mutations in exons 9, 11, 13, and 17 of the KIT gene and exons 12, and 18 of the PDGFRA gene were defined as KIT/PDGFRA wild-type and they accounted for ~15–20% of GISTs." (PMID 26848617, 2016). "About 10-15% of adult gastrointestinal stromal tumors (GIST) and the vast majority of pediatric GIST do not harbour KIT or platelet-derived growth factor receptor alpha (PDGFRA) mutations." (PMID 25239601, 2014). "Gastrointestinal stromal tumors (GISTs) lacking of KIT and PDGFRα mutations presented significantly higher prevalence of IGF-1R amplification compared to mutated ones." (PMID 22415797, 2012). "We present for the first time a malignant gastrointestinal stromal tumor of the gallbladder, immunoreactive for platelet-derived growth factor receptor alpha (PDGFRA) and negative for CD 117 antigen (c-KIT)." (PMID 21760661, 2011). "Interesting data have been reported also on IGF1r in gastrointestinal stromal tumors (GISTs) especially in children and in young adult patients whose disease does not harbour mutations on KIT and PDGFRA and are poorly responsive to conventional therapies." (PMID 21078151, 2010). "Gastrointestinal stromal tumor (GIST) should be the first alternative possibility when considering a differential diagnosis of an IFP because it also predominantly comprises spindle cells and shows high and diffuse expression for CD34, with a portion expressing PDGFRA as is also observed in IFP." (PMID 39960966, 2025). "Avapritinib showed clinical activity against PDGFRA D842V‐mutant and later‐line KIT‐mutant gastrointestinal stromal tumors (GIST)." (PMID 40656546, 2025). "Pathogenic variants in SDHx genes, initially considered as susceptibility genes only for PPGLs, are in fact also recognized to be associated with a risk of renal cancer and wild GIST (gastrointestinal stromal tumors without mutation in the KIT and PDGFRA genes)." (PMID 39457697, 2024). "In patients with gastrointestinal stromal tumors (GIST), ctDNA harboring CKIT or PDGFRA was used as a tumor-specific biomarker and the amount of mutant-free circulating DNA was correlated with disease course." (PMID 32010431, 2020). "About 10-15% of adult gastrointestinal stromal tumors (GIST) and the vast majority of pediatric GIST do not harbour KIT or platelet-derived growth factor receptor alpha (PDGFRA) mutations (J Clin Oncol 22:3813–3825, 2004; Hematol Oncol Clin North Am 23:15–34, 2009)." (PMID 25239601, 2014). "Due to these other activities, imatinib is effective at treating gastrointestinal stromal tumors (GIST) which are dependent on c-KIT, many other cancers, and steroid refractory Graft-versus-Host disease which requires PDGFRA activity." (PMID 25685324, 2014).
gastrointestinal stromal tumor (continued). "However, the data show that this is true for its inhibition of VEGFR2, a target of angiogenic drugs, but not for PDGFRα, a target in gastro-intestinal stromal tumours, an indication for which regorafenib is approved as well." (PMID 24651269, 2014). "Postoperative pathology and immunohistochemistry (CD117, DOG-1, CD34 positive) confirmed that all masses were gastrointestinal stromal tumors (GIST)(including uterine Extra-GIST (EGIST)), and C-kit/PDGFRA gene mutation was negative." (PMID 42305962, 2026). "PDGF, a fundamental protein stored in platelet α-granules, along with its receptors (PDGFRα and PDGFRβ), is expressed in numerous malignant cells and tissues, including NSCLC, gastrointestinal stromal tumors (GIST), and pancreatic, breast, ovarian, hepatocellular, and neuroendocrine cancers." (PMID 39737184, 2024). "Gastrointestinal stromal tumor (GIST) initiation and evolution is commonly framed by KIT/PDGFRA oncogenic activation, and in later stages by the polyclonal expansion of resistant subpopulations harboring KIT secondary mutations after the onset of imatinib resistance." (PMID 32024476, 2020). "In gastrointestinal tract cancers, NTRK fusions are relatively highly detected in gastrointestinal stromal tumor (GIST), primarily in cases without KIT, PDGFRA, or RAS mutations, and in colorectal cancer, most frequently in Microsatellite Instability (MSI)-high tumors." (PMID 41516212, 2025). "A very low percentage of C-KIT negative gastrointestinal stromal tumors (GIST) contain PDGFRA mutations, benefiting from imatinib in a way comparable to CML patients do, although C-KIT positive GIST also respond not only to imatinib but also sunitinib, eventually developing resistance." (PMID 29455659, 2018). "This phenomenon is for instance well known in the subset of gastro-intestinal stromal tumors that are wild-type for the KIT and PDGFRA genes and generally do not respond to TKIs such as Imatinib and Sunitinib." (PMID 27741505, 2017). "We report the identification of clinically relevant and previously unreported genomic alterations in gastrointestinal stromal tumors (GISTs) lacking genomic alterations in KIT, PDGFRA, SDH, and the RAS pathway." (PMID 27974047, 2016).
glioma (304 papers, 2007 to 2026). A benign or malignant brain and spinal cord tumor that arises from glial cells (astrocytes, oligodendrocytes, ependymal cells). "PDGFRA alterations (mutation and amplifications) can be seen in pediatric thalamic high-grade gliomas." (PMID 41596345, 2026). "Since the pediatric high-grade gliomas carrying PDGFRA alteration are associated with worse outcome, TKI can be used among these patients to prolong the survival." (PMID 41596345, 2026). "In Olig2-deficient glioma models, the downregulation of PDGFRA signaling is accompanied by feedback upregulation of the EGFR pathway to sustain tumor growth." (PMID 40428395, 2025). "The most common are mutations leading to amplification of PDGFRA in approximately 15% of pediatric high-grade gliomas and lead to significantly higher PDFGRA expression." (PMID 40094009, 2025). "Out of 13,250 glioma cases available in the register, 25 (24 glioblastomas and 1 diffuse glioma) showed 32 intergenic PDGFRA structural variants (SVs)." (PMID 40819143, 2025). "Treatment of IDH-mutated glioma spheroids with demethylating agents can partially restore insulator function and down-regulate PDGFRA." (PMID 40901634, 2025). "Amplification and mutation of platelet-derived growth factor receptor A (PDGFRA) are frequently observed in high-grade gliomas, particularly glioblastoma, and correlate with a more aggressive phenotype." (PMID 39606019, 2024). "Previous study has revealed that high frequency of PDGFRA mutations in high-grade gliomas, and overexpression of PDGFRA in oral cancer patients." (PMID 38167072, 2024). "Hypermethylation of CTCF insulators has been shown to cause overexpression of PDGFRA, an oncogene that contributes to tumor proliferation and invasion in glioma." (PMID 39491527, 2024). "-Almost exclusively in proneural subtype-Mutations in PDGFRA lead to enhanced signaling through the PDGFRα pathway, which promotes glioma cell proliferation, migration, and angiogenesis." (PMID 38534769, 2024). "The transmembrane receptor PDGFRA is overexpressed, amplified, mutated, or truncated in gliomas and is the second most frequently mutated tyrosine kinase receptor in glioblastomas." (PMID 37332354, 2023). "Because PDGFRA is frequently amplified or mutated in pediatric gliomas, there is a need to replicate different PDGFRA variant types found in pHGG via modeling." (PMID 35978801, 2022). "used Cre recombinase to knock in mutant PDGFRA combined with Ink4a/ARF -/- in OPCs of mice to cause development of brain tumors resembling anaplastic human gliomas, emphasizing the importance of PDGFRA as an early driver of malignant transformation of OPCs." (PMID 35978801, 2022). "Examining its underlying mechanism, we showed that circCDK14 accelerates glioma progression by sequestering miR-3938 and ultimately regulating PDGFRA, a well-known glioma oncogene." (PMID 35002529, 2022). "Our results demonstrate that G34-DHG is a new high-grade glioma with high frequency of PDGFRA and MUC gene family mutations." (PMID 35109850, 2022). "Like EGFR, PDGFRA was reported to be highly expressed, amplified, mutated, or truncated in gliomas 37-40." (PMID 35002529, 2022). "Future studies should evaluate the role of PDGFRA and H3 K27 alterations in predisposition to CC invasion by glioma cells and worse clinical outcomes." (PMID 35626112, 2022). "In adult glioblastomas, the highest levels of CD73 are associated with EGFR activation and astrocyte-like differentiation, whereas in pediatric gliomas CD73 expression is linked to PDGFRA activation and OPC-like differentiation." (PMID 35973991, 2022). "In glioma, somatic alterations of PDGFRA include missense mutations, in-frame insertions or deletions, gene amplification and fusion." (PMID 35109850, 2022). "PDGFRA is an important receptor tyrosine kinase in glial development and a recurrent driver in high-grade gliomas PDGFRA mutation and the PDGFRA signaling pathway were reported to play potent oncogenic roles in G34-DHGs." (PMID 35109850, 2022).
glioma (continued). "Several genetic rearrangements in PDGFRA have been identified in gliomas, but their diagnostic or prognostic significance is unclear." (PMID 35888045, 2022). "In GBM and in IDH mutant lower-grade (WHO Grades II/III) glioma, PDGFRA amplification is associated with shorter progression-free survival and OS and it is an independent prognostic factor." (PMID 35109850, 2022). "Cui and collaborators demonstrated that the upregulation of PDGFRα was critical for glioma tumorigenesis mediated by colon cancer-associated transcript 1 (CCAT1), a long non-coding RNA36." (PMID 33568640, 2021). "CD133 was positively associated with GB aggressiveness and PDGFRα, one of the critical genes involved in glioma progression and the second most frequently overexpressed TRK in GB." (PMID 35052687, 2021). "By contrast, PDGFRA is often genetically amplified or mutated in many types of gliomas, including diffuse midline glioma (DMG) where OPCs are considered the most likely cell‐of‐origin." (PMID 34480532, 2021). "Several PDGFRA alterations have been detected in gliomas, including amplification, missense mutation, frameshift mutation, in-frame insertion or deletion, and rearrangement." (PMID 34393714, 2021). "Inhibiting PDGFR activity with crenolanib decreased CHSY1-induced malignant characteristics of GL261 cells and prolonged survival in an orthotopic mouse model of glioma, which underlines the critical role of PDGFRA in mediating the effects of CHSY1." (PMID 32019907, 2020). "Patients’ age, KDELC2 expression, IDH1, ATRX, neurofilament, p-AxL, Nur77, H3Lys27, and PDGFRA were associated with glioma patients’ overall prognosis." (PMID 32927743, 2020). "Although the PDGFRA gene is amplified or mutated in some pediatric high-grade gliomas and DIPGs, these alterations are very rarely seen in ACVR1-mutant tumors." (PMID 32142668, 2020). "Detection of a BRAF V600E mutation next to mutations in NF1 and JAK3 as well as deletions of KIT and PDGFRA led to the diagnosis of a pediatric-type low-grade glioma or ganglioglioma." (PMID 32758285, 2020). "In IDH-mutant gliomas, PDGFRA insulator loss is associated with an altered locus topology that allows the PDGFRA promoter to interact with an enhancer in an adjacent TAD9." (PMID 31534142, 2019). "We previously reported that disruption of an insulator in the PDGFRA locus by aberrant DNA methylation is associated with increased expression of the oncogene in IDH-mutant gliomas." (PMID 31534142, 2019). "Given the association of PDGFRα with IDH-mutant glioma, the use of PDGFA as an oncogenic driver seems more relevant because PDGFA activates only PDGFRα." (PMID 30416682, 2018). "The other three groups, PDGFRA-associated gliomas and EGFR-low and PDGFRA-low gliomas, were associated with a better prognosis." (PMID 30279357, 2018). "For example, the PDGFRA gene is known to be mutated in the proneural subtype of glioma, its expression was elevated ~16-fold in BT142 as compared with GB10." (PMID 29062039, 2017). "PDGFRA amplifications are also described as a bad prognostic marker in adult IDH1 mutated high-grade glioma and adult anaplastic astrocytoma." (PMID 29312620, 2017).
glioma (continued). "Another study revealed that the high expression of phosphorylated PDGFRα has a significant association with malignant histology in pediatric gliomas." (PMID 26248280, 2015). "PDGFRα is another critical gene in glioma biology, as it is the second most frequently mutated TRK in GBM, following EGFR." (PMID 25380967, 2014). "We recently discovered that activation of a receptor tyrosine kinase implicated in the pathology of gliomas, human platelet-derived growth factor alpha receptor (PDGFRα) is required for HCMV infection." (PMID 24658280, 2014). "Using several approaches to overexpress gB in glioma cells, we intended to simulate chronic activation of the PDGFRα, which has been linked to disease progression in glioblastoma." (PMID 24658280, 2014). "Up-regulated ERK phosphorylation is associated with a reduction of surface PDGFRA expression and a decline of glioma cell proliferation." (PMID 24489888, 2014). "Compared to the established close association between EGFR activation and EGFR gene amplification and mutation, the amplification, rearrangement and mutation of PDGFRA gene is present only in a small fraction of gliomas." (PMID 24489888, 2014). "Our findings show that glioma cell proliferation is associated with surface expression of PDGFRA, which in turn is efficiently decreased by U0126." (PMID 24489888, 2014). "PDGFRA overexpression is thus unlikely caused by PDGFRA gene amplification in the majority of gliomas." (PMID 23630597, 2013). "Conversely, PDGFRA-low and PDGFRA-intermediate gliomas were associated with significantly higher frequency of EGFR amplification compared to PDGFRA-high gliomas." (PMID 23630597, 2013). "The occurrence of PDGFRA expression and its association with the pathological and clinical parameters of gliomas have been controversial." (PMID 23630597, 2013). "Our findings showed that in adulthood gliomas as analyzed in this report, amplification of PDGFRA gene was unlikely the main cause of PDGFRA overexpression in gliomas." (PMID 23630597, 2013). "Six of the 51 gliomas in the PDGFRA-high group showed gain of PDGFRA, and heterozygous loss of PDGFRA gene was found in 10 cases in this group." (PMID 23630597, 2013). "PDGFRA gene amplification and mutation in gliomas with high expression levels was also reported previously." (PMID 23630597, 2013). "To address the causes of PDGFRA overexpression in gliomas, we first analyzed the 50k HindIII SNP data in the Rembrandt data set using dChip and GISTIC2.0." (PMID 23630597, 2013). "The frequency of IDH1 mutation was significantly higher in PDGFRA-high gliomas compared to PDGFRA-low gliomas." (PMID 23630597, 2013). "A previous report described a significant association between PDGFRA expression, as analyzed at the mRNA level by in situ hybridization and LOH17p in human gliomas." (PMID 21209724, 2011). "Here, we investigated the prevalence of PDGFRA-activating mutations and gene amplification in gliomas." (PMID 19707201, 2009). "In this study, we intended to analyse the expression of PDGFA and its receptor PDGFRA, as well as the underlying genetic (mutations and amplification) mechanisms driving their expression in a large series of human gliomas." (PMID 19707201, 2009). "The DHG H3G34mut tumours may have co-driver PDGFRA mutations which provide astrocytic features, hence why they are still classified as gliomas." (PMID 40986124, 2025). "PDGFRA plays a role in normal gliogenesis of the central nervous system and PDGFRA high-level amplification and gain has been associated with high grade malignancy in gliomas." (PMID 38012788, 2023).